IL6 (interleukin 6)
Diseases named in the same sentence as IL6 in open-access papers (continued):
Sharing a sentence is not in itself a finding about the gene and the disease.
tumor (continued). "IL-6 levels in tumor tissues is also higher than adjacent normal esophageal tissues." (PMID 26761210, 2016). "As a recent study reported that GA suppressed lipopolysaccharide-induced nuclear factor-kB signaling, resulting in decreased production of IL-6, we wondered if GA inhibits Stat3 phosphorylation and subsequently suppresses Stat3-mediated tumor proliferation, especially in TKIR cells." (PMID 27419630, 2016). "Collectively, IL-6 promotes tumour self-seeding by CTCs in a nude mouse model." (PMID 26623559, 2016). "IL-6 suppression or JAK/STAT3 pathway inhibition reduced CTC seeding in primary tumours." (PMID 26623559, 2016). "Notably, our analysis of cytokine and chemokine transcript levels in the DTX-treated senescent tumor cells demonstrated upregulation of numerous cytokine species including those implicated in supporting tumor growth (such as CXCL1, IL-1 or IL-6)." (PMID 27448982, 2016). "All these factors unite to their receptors in the membrane of the tumour cells stimulating the growth and the synthesis of PTHrP, such as multiple cytokines -like IL-1, IL-6, IL-11, IL-8-, which induce osteolysis to which the vascular endothelial growth factor or VEGF is added." (PMID 28105072, 2016). "In addition to HIF-1α regulation of inflammation, HIF-2α can regulate macrophage function in tumor models, eosinophil function in the lung, and IL-6 secretion from endothelial cells (49, –, 51)." (PMID 27624128, 2016). "Interestingly, the BCL1 tumor cells also secreted IL-6, which has been described to contribute to the impairment of immune responses in the tumor milieu." (PMID 27959896, 2016). "In fact, AT is recognized now as potent endocrine organ by secreting pro-inflammatory cytokines [such as tumor necrosis factor-alpha (TNF-α) and interleukin-6 (IL-6)] and adipokines (such as leptin) in the tumor microenvironment, with great significant impact on both tumor and immune cells." (PMID 27066006, 2016). "Furthermore, it is known that OS behaviour is adversely influenced by osteoclast bone-resorption and by IL-6 levels at the tumor site and that IL-6 can increase chemoresistance of human OS cells." (PMID 27851822, 2016). "IL-6 is one of the key cytokines involved in the proliferation and differentiation of tumour cells." (PMID 27538520, 2016). "Thus, Nrf2 contributes to the anti-tumour immunity through dual pathways, the repression of IL-6/IL-1 and/or ROS elimination in MDSCs." (PMID 27211851, 2016). "In addition, CAF have the capability to recruit immune cells into the tumor region via altering the expression of IL6, CCL2, or NF-kB signals." (PMID 26790618, 2016). "The present findings strengthen the rationale for Notch-tailored therapies in MM providing evidences that knocking down MM-derived JAGGED ligands may reduce MM tumor burden by decreasing the amount of IL-6 in the BM niche." (PMID 27463014, 2016). "On the other hand as TNFα and IL-6 signaling have been also shown to be involved in HCC oncogenesis, the observed anti-inflammatory effects of IGF-I encoding vectors might oppose tumor development in the cirrhotic liver." (PMID 27658043, 2016). "Moreover, it was shown that IL-6 promotes tumor growth by VEGF-dependent angiogenesis in particular via a STAT3 pathway." (PMID 27538520, 2016). "The tumor growth increased significantly in the presence of IL-6." (PMID 27769047, 2016). "Contribution of MSCs to tumor development is highly dependent on IL-6 activities." (PMID 27630452, 2016). "However, clinical chickens with neoplasms showed IL-6, IL-1β and IFN-β levels that were significantly altered within the clinical group." (PMID 27252695, 2016). "In addition to its role in inflammation, IL-6 is known to regulate tumor development, including initiation, promotion, malignant conversion, invasion, and metastasis, and a relationship between IL-6 expression and cancer pathology has been reported." (PMID 26579954, 2016).
tumor (continued). "It was widely accepted that the host-related inflammatory response plays an important role in tumorigenesis, tumor progression, and metastasis through recruitment of regulatory T lymphocytes and cytokines, including interleukin-1 (IL-1), IL-6, and tumor necrosis factor α." (PMID 26438061, 2016). "However, in a few cases, ascites levels were unexpectedly high in view of the low expression of the corresponding mRNAs in tumor cells and TAMs, e.g. IL-6 and VEGF-C." (PMID 27215396, 2016). "Furthermore, it provides more results to support the involvement of IL-6 in tumor-promoting inflammation in this malignancy, and the data also suggest that IL-6 interacts differentially with the tumorigenic mechanisms of mutated BRAF and RAS in CRC." (PMID 27738330, 2016). "IL6 can promote B-cell differentiation, which is thought to prevent tumor growth." (PMID 27329590, 2016). "Collectively, these data demonstrate that while PDTC treatment attenuated body weight and muscle mass loss, systemic inflammation related to plasma IL-6 and total tumor number remained elevated regardless of PDTC treatment in ApcMin/+ mice." (PMID 27449092, 2016). "Therefore, it will be necessary to isolate CD133+ and CD133– cells from tumor tissues and investigate the IL-6 role to understand the IL-6 effect on growth of CD133+ and CD133– cells." (PMID 26675547, 2016). "g., IL6 and TNF) that kill cancer cells; however, MΦ2 macrophages the predominant tumor associated macrophages in late stage cancers release anti-inflammatory IL-10, and a variety of growth factors (VEGF, FGF etc), that promote growth and vascularization of the cancer mass." (PMID 27231721, 2016). "In addition to the effects on the tumor itself, recent studies show IL-6 controls tumor growth by activating the normal stromal cells located in the tumor microenvironment." (PMID 27756885, 2016). "M1 macrophages can be activated by Th1 cytokine interferon γ (IFNγ) and microbial products, and they express high levels of pro-inflammatory cytokines (e.g. TNFα, IL-1, IL-6, IL-12 and IL-23), and inducible nitric oxide synthase (iNOS), and are capable of killing pathogens and tumor cells." (PMID 26799669, 2016). "The potent anti-inflammatory and anti-tumor effects of embelin were demonstrated by the findings that this agent dramatically reduced the infiltration of macrophages and decreased the expression of TNFα, IL-6, IL-1β, COX-2 and iNOS in colonic tissues." (PMID 26799669, 2016). "The change in IL6 levels in study II was sufficiently heterogeneous between tumours to nullify the highly significant correlation between the A and B samples in study I, suggesting that the IL6 changes were more related to the effects of the initial biopsy than to the short delays around surgery." (PMID 27036195, 2016). "When tumors were palpable, IL-6 was injected subcutaneously around the tumor twice a day." (PMID 27769047, 2016). "There is positive link between the level of IL-6 in serum and tumor tissue." (PMID 26761210, 2016). "However, at a later stage, CAFs become activated by several tumor-secreted factors, such as TGFβ1, PDGFα/β, basic fibroblast growth factor (b-FGF), or interleukin 6 (IL-6), resulting in the promotion of both tumor growth and progression." (PMID 27270649, 2016). "In addition, IL-6 directly promotes the accumulation of MDSCs in tumors, thereby facilitating tumor progression." (PMID 27148488, 2016). "Moreover, the abundant of inflammation cytokines secreted by activated macrophages in the adipose tissue, such as TNFα, IL-6, etc., constitutes tumor microenvironment, which promotes tumor cell migration and invasion." (PMID 27247890, 2016). "Similarly, neutralization of IL-6 significantly enhanced the therapeutic efficacy of paclitaxel in mouse models of EOC by reducing tumor growth." (PMID 27825119, 2016). "Taken together, HVJ-E stimulates neutrophil activation and may also exert a protective effect on activated neutrophils by increasing IL-6 levels in the tumor bed." (PMID 27259252, 2016).
tumor (continued). "IL-6, an important pro-inflammatory cytokines in infection and tumor, could induce differentiation of MDSC both in vitro and in vivo." (PMID 26797765, 2016). "Besides, IL-6 has been shown to induce expansion of cancer stem-like cells in tumors, as well as Th17 immune response, thus stimulating tumor progression." (PMID 27630452, 2016). "Moreover, the physiological role of IL-6 has been shown to promote not only tumour proliferation, but also metastasis and symptoms of cachexia." (PMID 27034885, 2016). "Furthermore, neutralization of IL-6 had a very similar effect, showing virtual rescue of enhanced tumor growth and osteoclast activation by HFD." (PMID 27049717, 2016). "This indicates that lower levels of MCP-1 and IL-6 might benefit and enhance the immune response of subjects against neoplastic diseases." (PMID 26794215, 2016). "IL-6 can turn on expression of multidrug resistance protein 1 (mdr1), allow cells to evade apoptosis, and attenuate the antigen-presenting capabilities of dendritic cells in the tumor microenvironment to repress an immunogenic response." (PMID 27531896, 2016). "Notably, HIC1 is a tumor suppressor through inhibiting the transcription of IL-6 by sequence-specific binding on its promoter." (PMID 27107418, 2016). "Furthermore, PSCs can directly interact with immune cells as they secrete interleukin (IL)-6 and thus stimulate the recruitment of myeloid-derived suppressor cells (MDSCs) into the tumor microenvironment." (PMID 27687804, 2016). "However, Selumetinib decreased IL-6 protein by 35.04% (P < 0.05) in tumor lysates, a finding confirmed by immunohistochemistry of tumor sections." (PMID 28149280, 2016). "In addition, the IL-6 role in the milieu of the tumor microenvironment is considered clinically important because there is a report indicating the interaction of IL-6 with other molecules in affecting these cells' growth." (PMID 26675547, 2016). "The microenvironment of a tumour resembles that of a chronic wound where MSCs are attracted by the local release of inflammatory chemokines, such as chemokines, growth factors, and pro-inflammatory IL-6." (PMID 27845732, 2016). "This marked sensitivity of the immune C26 tumor microenvironment to corticosterone was also reflected by the correlation between anti-IL-6-induced decreased plasma levels of the hormone and increased mRNA levels of Cxcl9, Cxcl10, and Cxcl11 in food-restricted pre-cachectic C26-bearing mice." (PMID 27829137, 2016). "We found that tumor cells significantly promoted the IL-6 production in MSCs." (PMID 27340780, 2016). "Suppressing IL-6 inhibited in vivo tumour growth and metastasis." (PMID 26623559, 2016). "In addition, the astrocytes encourage tumour growth by the secretion of cytokines, la heparanasa, neurotrophic factors, TNFα, TGFβ, IL6, etc." (PMID 28105072, 2016). "Being different from normal cells, which phosphorylate STAT under stringent control, STAT3 is continuously phosphorylated in several neoplastic diseases via the overproduction of agonists, such as specific cytokines, namely, IL-6, and their respective cytokine receptors." (PMID 27190500, 2016). "However, the manner in which IL6 contributes to tumor progression by initiating autophagy has yet to be thoroughly investigated." (PMID 27163161, 2016). "Production of IL-6 and signaling are prerequisites for tumor progression." (PMID 27190500, 2016). "It is known that high expression levels of Jagged1, Notch 1 and Notch2 correlate with tumor progression of myeloma;44 in this context, it has been recently proposed an activating role of Notch on IL-6 proliferating signals in the bone marrow niche, which results in an enhancement of tumor growth." (PMID 27929540, 2016). "Expression of LAG-3 and PD-1 was up-regulated by IL-10, IL-6 and tumor-derived APCs." (PMID 26700461, 2016).
tumor (continued). "In addition to this, in the present study, the IL-6 mRNA expression was higher in the primary tumour tissues of PTC patients as compared to the corresponding adjacent normal tissues." (PMID 27034885, 2016). "IL-6 working in an autocrine feedback loop on tumor cells and MSCs may further drive proliferation in this setting." (PMID 27931212, 2016). "Additionally, IL-6 expression was related to the tumor grade in patients with HCC and had moderate predictive value in relation to HCC." (PMID 27589954, 2016). "Similarly, it has been found that lung tumor cell factors can induce proinflammatory phenotype in MSCs by activation of NF-κB, which is known to induce production of inflammatory factors with tumor-supporting roles such as IL-6, TGF-β, and IL-1." (PMID 27630452, 2016). "Similarly, IL-6 released from the tumor cells induce miR-17 and miR-20a down-regulation in TAMs which induces HIF-2α and transcription of proangiogenic genes." (PMID 27231010, 2016). "To test physiologically relevant concentrations of TNFα and IL-6 in illness, we included two combinations containing both TNFα and IL-6 that reflected plasma levels measured in C26 adenocarcinoma tumour-bearing mice or Lewis Lung tumour-bearing mice respectively." (PMID 27207102, 2016). "There are several cell types in the tumor microenvironment that potentially could secrete IL-6; stromal cells (e.g fibroblast, adipocytes) and cancer cells." (PMID 27329584, 2016). "Here we found that both TNF-α and IL-6 production by tumour cells is diminished upon Axl knockout." (PMID 28008921, 2016). "SOCS3 is predominantly considered a negative regulator of the IL-6 induced JAK/STAT pathway which can be constitutively active in CLL due to interaction with other cells in the tumor microenvironment, or due to treatment related complications such as cytokine release following tumor lysis." (PMID 27107422, 2016). "Therefore, tumor-induced IL-6 impairs the ketogenic response to reduced caloric intake, resulting in a systemic metabolic stress response that blocks anti-cancer immunotherapy." (PMID 27829137, 2016). "The classical and trans-signaling pathways are thought to contribute to the anti-inflammatory and pro-inflammatory activities of IL6, respectively, and the proliferation and survival of tumor cells are promoted by IL6 through both paracrine and autocrine mechanisms." (PMID 27163161, 2016). "Similarly, our in vivo results also indicated the infiltrated expression of IL-6 throughout the sectioned tumor tissue, emphasizing the potential autocrinal/paracrinal regulation." (PMID 27285760, 2016). "Notably, the level of IL-6 was elevated in G1-G3 prostatosphere-derived tumor xenografts being higher than those observed in ESE3KD adherent cells in culture." (PMID 27732936, 2016). "Utilizing IL-6 signaling inhibitors to target the tumor microenvironment and indirectly block cancer cell growth could be effective in treating and preventing breast carcinogenesis." (PMID 26840088, 2016). "Similarly, miR-92a is released from glioma cells and induces NK cell expression of IL-6 and IL-10, significantly attenuating the expression of NK cell-derived anti-tumor molecules, including perforin, Fas ligand, and IFN-γ." (PMID 27231010, 2016). "Presence of micrometastatic tumor cells in the liver may induce the Kupffer cells to produce a variety of cytokines (IL-1, IL-6, and TNF-a), which may modulate albumin synthesis by hepatocytes." (PMID 26880857, 2016).
tumor (continued). "Taking in account that IL-6 takes part in regulation of VEGF expression we can speculate that decreasing of level IL-6 after therapy of tumor with LIVP-GFP might lead to decreasing of VEFR’s level thus affecting tumour vasculature." (PMID 27538520, 2016). "Our results suggest that IL-6 blockade alone reduces tumor cell viability and promotes apoptosis." (PMID 27006530, 2016). "For example, STAT3 activation initiated by IL-6 in tumor-associated endothelial cells, TAM, and MSCs induces their ability to express VEGF and bFGF in a feed-forward loop that positively regulates angiogenesis within tumor tissues." (PMID 27756885, 2016). "The decreased secretion of IL-6 in the supernatant of irradiated cells supernatant may explain the growth inhibition in bystander tumor cells." (PMID 27561007, 2016). "To test whether senescence-derived IL-6 promotes tumour cell growth through MDSCs accumulation, we co-injected tumour cells with non-senescent or senescent MSFs into mice that were treated with an IL-6 neutralizing antibody." (PMID 27272654, 2016). "In this study, we explored the effects and mechanisms of IL-6 in tumour self-seeding." (PMID 26623559, 2016). "However, inhibition of STAT3 by AG490 increased the sensitivity of IL-6-treated tumor cells to doxorubicin." (PMID 27340780, 2016). "Of note, IL-6 level and macrophage number was raised at the tumor site." (PMID 27589729, 2016). "Moreover, a significant positive correlation was observed between the IL-6 protein and mRNA expression in the primary tumours of PTC patients." (PMID 27034885, 2016). "In hypoxic areas, TAMs stimulate angiogenesis by secreting TGF-β, VEGF, granulocyte macrophage (GM)-CSF, TNF-α, IL-1, IL-6, and IL-8, promote tumor cell migration and invasion via matrix metalloproteinases (MMPs), TNF-α, and IL-1 and induce immunosuppression via TGF-β, PGE2, and IL-10." (PMID 27044404, 2016). "Furthermore, pharmaceutical inhibition of IL-6 signaling was shown to decrease the rate of cachexia in tumor-bearing rodents." (PMID 26856534, 2016). "In addition, we found that blockade of IL-6 in MSC CM via specific neutralizing antibodies attenuated the protective effect of MSCs on Saos-2 tumor cells." (PMID 27340780, 2016). "Inhibition of IL-6 or of downstream JAK2 blocked HFD-induced tumor progression." (PMID 27049717, 2016). "IL-6 blockade had a synergistic effect on promoting tumor cell apoptosis when combined with CBP." (PMID 27006530, 2016). "Examples of key players of cancer-related inflammation (CRI) include tumor-infiltrating lymphocytes, tumour-associated macrophages (TAMs), the secretion of cytokines such as TNF, IL-1, IL-6, and chemokines such as CCL2 and CXCL8, in addition to the occurrence of tissue remodeling and angiogenesis." (PMID 27555866, 2016). "Moreover, it has been demonstrated that tumor cells and especially their secreted molecules or extracellular vesicles induce higher expression of IL-6 in MSCs, thus educating them to acquire tumor-supporting properties." (PMID 27630452, 2016). "Constitutive STAT3 phosphorylation in tumor cells is usually driven by the overproduction of key cytokines and growth factors, such as IL-6, IL-10, EGF, HGF, Her2/Neu, and VEGF, or their receptors, as well as aberrantly activated cytoplasmic kinases, such as Src, among others." (PMID 27148255, 2016). "The use of PDX mouse models to test the effectiveness of anti‐cytokine or anti‐chemokine antibodies (such as anti‐IL6 antibody) in reducing tumor growth is likely to become prevalent and our results suggest a note of caution in the design and interpretation of these studies." (PMID 26833741, 2016). "The elevated IL-6 levels correlated with intensive tumour growth in this group." (PMID 27538520, 2016).